METTL3 (methyltransferase 3, N6-adenosine-methyltransferase complex catalytic subunit)
Diseases named in the same sentence as METTL3 in open-access papers (continued):
Sharing a sentence is not in itself a finding about the gene and the disease.
pterygium (1 paper, 2021). A wedge-shaped fibrovascular lesion arising from the bulbar conjunctiva and extending to the cornea. "The decrease in m6A modification level caused by the downregulation of METTL3 may be an important reason for the development of pterygium, but further research is needed to clarify the exact mechanism." (PMID 34249924, 2021). "We found significantly downregulated m6A levels in pterygium compared to conjunctival tissues, especially by METTL3, which may be the pivotal regulator in pterygium." (PMID 34249924, 2021). "Both level of m6A and expression of METTL3 were decreased in pterygium." (PMID 34249924, 2021).
pulmonary disorders (1 paper, 2025). "In the context of lung diseases, METTL3 functions as a converging point for multiple regulatory signals that modulate fibrosis, inflammation, and tumorigenesis." (PMID 41515964, 2025). "Future studies should continue to investigate the cell-type–specific and disease-context–dependent roles of METTL3 across different lung disease models." (PMID 41515964, 2025). "As a core methyltransferase in the m6A modification pathway, METTL3 plays a complex role in the pathogenesis of lung diseases." (PMID 41515964, 2025). "Further research is needed to delineate how METTL3’s cellular regulation shapes its function in lung pathophysiology, and to evaluate the feasibility of pharmacological modulation (via inhibitors or activators) of METTL3 as a therapeutic approach for pulmonary disorders." (PMID 41515964, 2025). "Additionally, METTL3 is broadly upregulated across various fibrotic lung diseases, regulating classic pro-fibrotic pathways such as TGF-β and COL1A1." (PMID 41515964, 2025). "In the context of lung diseases, METTL3-mediated m6A modification regulates the expression of key genes involved in cellular proliferation, differentiation, inflammation, and cell death, highlighting its significant role in the initiation and progression of pulmonary pathology." (PMID 41515964, 2025). "In recent years, m6A RNA modification, largely driven by METTL3, has been recognized as a pivotal regulatory pathway in ALI/ARDS and other pulmonary diseases." (PMID 41515964, 2025).
pulmonary stenosis (1 paper, 2025). "We found that cardiovascular-specific Mettl3 knockout mice died postnatally and exhibited congenital cardiac defects in the right ventricle and outflow tract, including left pulmonary stenosis, ventricular septal defects, and right ventricular hypoplasia." (PMID 40303284, 2025). "As a result, Mettl3-CV KO mice exhibited severe left pulmonary stenosis." (PMID 40303284, 2025).
pulmonary tuberculosis (1 paper, 2022). A bacterial infection that affects the lungs and is caused by Mycobacterium tuberculosis. "The aim of the current study was to investigate the contributing role of gene variation and transcription levels among the m6A methyltransferases METTL3, METTL14, and WTAP in pulmonary tuberculosis (PTB)." (PMID 36569923, 2022).
retinal degeneration (1 paper, 2024). Degeneration of the retina. "Our data revealed that deletion of Mettl3 in rod and cone cells resulted in progressive retinal degeneration." (PMID 39728691, 2024). "Deletion of Mettl3 in rod cells led to progressive retinal degeneration, including progressive retinal thinning, impaired visual function, shortened photoreceptor outer segments (OS), and reduced expression of disk membrane proteins." (PMID 39728691, 2024). "To investigate the molecular mechanisms underlying retinal degeneration after Mettl3 deletion, we performed proteomic analysis on 2.5-month-old control and RKO mice, which started to exhibit retinal degeneration." (PMID 39728691, 2024). "In this study, a series of phenotypic experiments on Mettl3 RKO and CKO mouse models revealed that Mettl3 deletion resulted in retinal degeneration phenotypic features such as diminished visual function and photoreceptor degeneration." (PMID 39728691, 2024).
rheumatic diseases (1 paper, 2025). "However, the expression and function of METTL3 may vary across cell types and rheumatic diseases." (PMID 40506739, 2025).
right ventricular dysplasia (1 paper, 2025). "In addition, we found left ventricular hypoplasia existing in some of the Mettl3-CV KO mice as well, but less significantly than the incidence of right ventricular dysplasia." (PMID 40303284, 2025).
Rotavirus infection (1 paper, 2022). Infection with any of the rotaviruses. "Rotavirus infection increases the global frequency of m6A modifications, and METTL3 deficiency in intestinal epithelial cells (IECs) results in increased resistance to rotavirus infection." (PMID 35098923, 2022).
Sertoli Cell-Only Syndrome (1 paper, 2024). A type of male infertility in which no germ cells are visible in any of the biopsied SEMINIFEROUS TUBULES (type I) or in which germ cells are present in a minority of tubules (type II). "Interestingly, a much more profound defect in spermatogenesis was observed upon Vasa-Cre mediated Mettl3 or Mettl14 deletion, as SSCs were affected and germ cell development was arrested at the zygotene-like stage, exhibiting the Sertoli cell-only syndrome phenotype in adults." (PMID 39030605, 2024).
sleep disorder (1 paper, 2025). A change from the patient's baseline sleeping pattern, in the hours slept and/or an alteration/dysfunction in the stages of sleep. "Our results showed that Mettl3 loss leads to the decreased expression of NPY in neurons of VPM, and induces sleep disorder, especially NREM sleep disorder." (PMID 39905012, 2025). "Ectopic expression of Mettl3 and NPY reduced neuroinflammation and neuronal loss and rescued the disrupted sleep behavior, suggesting that neuronal NPY is an essential regulator of sleep and may serve as a therapeutic target for patients with sleep disorders." (PMID 39905012, 2025).
spermatocytoma (1 paper, 2022). "For instance, METTL3 silencing can be synergistically implemented with the glycolysis inhibitor 2-deoxyglucose (2-DG) to block HCC growth and combined inhibition of METTL3 and autophagy increases the sensitivity of spermatocytoma to cisplatin." (PMID 35794625, 2022).
spontaneous abortion (1 paper, 2023). Expulsion of the product of FERTILIZATION before completing the term of GESTATION and without deliberate interference. "Recently, the role of METTL3-mediated RNA methylation of m6ZBTB4 in trophoblastic invasion and recurrent spontaneous abortion (RSA) has been highlighted." (PMID 37742034, 2023).
status epilepticus (1 paper, 2025). Status epilepticus is defined as a continuous seizure lasting more than 30 min, or two or more seizures without full recovery of consciousness between any of them. "The upregulation of METTL3 and METTL14 in hippocampus was demonstrated in epileptic rats at 8 and 12 weeks after status epilepticus induced by pilocarpine." (PMID 40534269, 2025).
stress-related disorder (1 paper, 2024). Stress-related disorders are mental health disorders that are a result of an atypical response to both short and long-term anxiety due to physical, mental, or emotional stress. "Moreover, previous studies showed that not only METTL3 but also METTL14 plays a crucial role in synaptic plasticity and stress-related disorders such as depressive behavior." (PMID 38453794, 2024).
synovial sarcoma (1 paper, 2024). "Among them, METTL3, YTHDC1, YTHDC2, RBMX, and ELAVL1 were significantly upregulated in synovial sarcoma tissue." (PMID 38549939, 2024).
teratoma (1 paper, 2020). A non-seminomatous germ cell tumor characterized by the presence of various tissues which correspond to the different germinal layers (endoderm, mesoderm, and ectoderm). "In vivo, METTL3–/– ESCs showed a poor ability to differentiate into mature teratomas, and hematoxylin-eosin staining (H&E) staining suggested that KO teratomas could not differentiate into the three germ layers." (PMID 32850871, 2020).
testicular cancer (1 paper, 2020). A primary or metastatic malignant neoplasm that affects the testis. "From the limited studies available, we found that METTL3 and METTL14 have different expression patterns in four types of urological cancer (kidney, bladder, prostate, and testicular cancer)." (PMID 32765970, 2020). "In this review, we summarize the current research results for METTL3 and METTL14 and identify potential pathways involving these enzymes in kidney, bladder, prostate, and testicular cancer." (PMID 32765970, 2020).
thymic tumor (1 paper, 2021). "Various studies have reported that altered expression of METTL3 is associated with an aggressive malignant phenotype and favors migration and invasiveness, but its role in Thymic Tumors remains unknown." (PMID 34530916, 2021). "This study highlighted METTL3 as a tumor promoter in Thymic tumors and c-MYC as a promising target to be exploited for the treatment of TET." (PMID 34530916, 2021). "Moreover, we evaluated whether METTL3 and its downstream target c-MYC may represent powerful targets to improve the treatment of thymic tumors." (PMID 34530916, 2021).
thyroid tumours (1 paper, 2024). "In addition, thyroid tumours were larger in Mettl3 KO mice than in WT mice." (PMID 38993572, 2024).
uremia (1 paper, 2023). A clinical syndrome associated with the retention of renal waste products or uremic toxins in the blood. "For example, METTL3 can be used as a therapeutic target and as an early diagnostic indicator of kidney diseases such as ischemia‒reperfusion injury, cisplatin-induced AKI and obstructive nephropathy; the demethylase FTO can be used as a therapeutic target for DN and uremia." (PMID 38066436, 2023).
valvular heart disease (1 paper, 2022). "METTL3 can promotes osteogenic differentiation of human aortic valve interstitial cells by inhibiting twist-related protein 1 (TWIST1) expression through an m6A-dependent pathway, aggravating valve calcification and leading to the development of valvular heart disease." (PMID 35836571, 2022).
ventricular septal defect (1 paper, 2025). The presence of a defect (opening) in the septum that separates the two ventricles of the heart. "Mettl3 deficiency-induced downregulation of MEF2A, SOX4, and SOX11 expression could lead to congenital cardiac defects, including left pulmonary stenosis, ventricular septal defects, and right ventricular hypoplasia." (PMID 40303284, 2025).
Wilms tumor (1 paper, 2022). An embryonal neoplasm characterized by the presence of epithelial, mesenchymal, and blastema components. "For example, several SNPs in METTL3 and METTL14 genes have been associated with neuroblastoma, Wilms’ tumor, acute lymphoblastic leukemia, and autoimmune thyroid disease." (PMID 36569923, 2022).
withdrawal syndrome (1 paper, 2025). "Given METTL3’s role in mRNA stability, translation, and synaptic plasticity, its downregulation in the striatum may contribute to the dysregulation of the dopaminergic system, an essential component in the development of opioid addiction and withdrawal syndrome." (PMID 40362608, 2025).
tumor (965 papers, 2017 to 2026). "Orthotopical implantation of HCC cells in the fibrotic liver showed that HSC-specific METTL3 deficiency significantly increased tumor burden." (PMID 42030359, 2026). "Researchers have found that METTL3 is upregulated in a variety of tumors, and increased m6A deposition is associated with increased tumor angiogenesis." (PMID 40356596, 2025). "Abnormal m6A methylation patterns found in various cancers affect tumor progression and the tumor microenvironment, being often linked to methyltransferase-like 3 (METTL3) activity." (PMID 40868849, 2025). "The identification of the circMVP/METTL3/β-catenin/B7-H3 signaling axis provides new insights into the molecular mechanisms underlying immunosuppression and tumor progression, identifying new immunotherapeutic targets for CRC." (PMID 39744434, 2025). "When METTL3 activity was disrupted, there were increases in IL-8 secretion and recruitment of tumor-associated neutrophils." (PMID 40243425, 2025). "Other notable associations included LINE-1, linked to tumor invasiveness, and METTL3, which appears to influence cell growth regulation in GH-secreting pituitary adenomas (GH-PAs)." (PMID 39859246, 2025). "Third, O-GlcNAcylation drives immune evasion and tumor progression by regulating tumor-associated macrophage polarization, while METTL3 modulates the tumor microenvironment through m6A-dependent mechanisms." (PMID 40651967, 2025). "In BCa, high expression of METTL3 is thought to be associated with tumor aggressiveness and metastasis." (PMID 40678060, 2025). "In HCC, high expression levels of m6A writers, particularly METTL3, are associated with poor prognosis, as they enhance PD-L1 levels and subsequently inhibit T cell-mediated anti-tumor responses." (PMID 40034695, 2025). "Overexpression of METTL3 is linked to tumor progression, reinforcing the relevance of m6A in cancer biology." (PMID 40389988, 2025). "Dose-dependent reduction in proliferation and viability of PaCa-2 and Huh7 tumor cell lines via lowering of mRNA METTL3 level.Its mechanism is associated with PI3K/Akt/mTOR, Wnt/b-catenin, and MAPK/ERK1/2 pathways." (PMID 41157107, 2025). "In the context of HCC, METTL3 overexpression has been linked to poor prognosis and increased tumor growth." (PMID 40451925, 2025). "For example, the deletion of Mettl3 in mouse myeloid cells promotes tumor growth and metastasis in vivo by increasing regulatory T cell (Treg) infiltration into tumors and reducing PD-1 checkpoint blockade efficacy in Mettl3-deficient mice." (PMID 40176140, 2025). "In colorectal carcinoma, histone lactylation has been implicated in driving METTL3-mediated RNA m6A modification, promoting immune suppression in tumor-infiltrating myeloid cells and mediating tumor immune evasion." (PMID 39990209, 2025). "The analysis of TCGA RNA-seq data revealed evidence of an association between METTL3 and immune response in BCa tumour specimens, as low METTL3 expression correlated with an increased expression of genes involved in immune-related pathways." (PMID 41310336, 2025). "For instance, the HBV-encoded HBx protein recruits the METTL3/METTL14 complex to chromatin regions of tumour suppressors such as PTEN, facilitating their destabilization via YTHDF2 binding and promoting oncogenic PI3K – AKT signalling." (PMID 40793828, 2025). "To further explore the molecular mechanisms underlying the tumor‐suppressive effects of METTL3 in hepatocarcinogenesis, we conducted RNA‐sequencing on liver tissues from two groups of mice 3 weeks post‐HTVI (four individuals per group)." (PMID 40103332, 2025). "In these mice, the loss of Mettl3 accelerated dedifferentiation and tumor progression compared to TPO-Cre/Mettl3fl/fl/BrafV600E mice." (PMID 39874138, 2025). "Higher METTL3 expression was associated with immunosuppressive phenotypes, such as increased infiltration of tumor-associated macrophages, regulatory T cells, and cancer-associated fibroblasts (p < 0.001)." (PMID 40177651, 2025).
tumor (continued). "Studies have demonstrated that PD-1 checkpoint blockade therapy exhibits diminished efficacy in METTL3-deficient mice, positioning METTL3 as a potential target for tumor immunotherapy." (PMID 39897038, 2025). "In BCa, METTL3 regulates the PI3K/AKT pathway associated with tumor angiogenesis and promotes tumor angiogenesis by modulating TEK and VEGFA." (PMID 39295872, 2024). "Conditional lymphatic Mettl3 knockout effectively inhibits corneal and tumor‐associated lymphangiogenesis, suggesting a potential role for antilymphangiogenic therapies alongside antiangiogenic approaches." (PMID 39372388, 2024). "Overall, METTL3 deficiency alters the m6A landscape in critical transcripts, resulting in reduced NK cell infiltration in the tumor microenvironment, decreased sensitivity to IL-15 overexpression, and impaired clonal expansion in several peripheral organs." (PMID 39497033, 2024). "By comparing the METTL3 expression in the primary tumour between these groups, we observed a significant association between high METTL3 expression and a more advanced lymph node stage." (PMID 38238831, 2024). "The loss of Mettl3 (Mettl3fl/fl-Ncr1Cre/+) disrupts NK cell homeostasis and impedes their infiltration and function within the tumor microenvironment." (PMID 39416774, 2024). "Increased METTL3 expression is associated with advanced T stage, poor tumour differentiation, lymphatic metastasis, and a poor overall survival rate in HNSCC and OSCC." (PMID 39822792, 2024). "Tumour‐associated macrophages in colorectal cancer have also been found to promote oxaliplatin resistance by influencing METTL3‐mediated TRAF5 m6A modification and programmed necrosis." (PMID 38572667, 2024). "The promotion of cancer in the majority of tumours is associated with the upregulation of METTL3 expression; however, the mechanism underlying its role is different." (PMID 38291427, 2024). "Recent studies have revealed that METTL3 upregulation in OVC is closely linked to tumour grade and OS rate." (PMID 38332508, 2024). "Their investigation of genes associated with AKR1B10 led to the discovery that the tumor-promoting function of methyltransferase 3 (METTL3) relied on the N6-methyladenosine (m6A) modification of AKR1B10." (PMID 39737179, 2024). "METTL3 has been reported to have a favourable effect on tumour growth and is a risk factor for cancer prognosis in various tumour." (PMID 38473842, 2024). "Deletion of METTL3 impairs the proliferation, differentiation, and cytokine secretion of iNKT cells, leading to a deficiency in tumor resistance." (PMID 39372415, 2024). "In CRC, mitochondrial metabolic reprogramming in cancer cells is inhibited by apoptosis caused by regulation of the RNA-binding protein RALY, while METTL3 can affect tumor development by targeting RALY." (PMID 39033180, 2024). "Nevertheless, the underlying mechanism by which METTL3 promotes tumour growth in LUAD remained unclear." (PMID 39095708, 2024). "Kyoto Encyclopedia of Genes and Genomes (KEGG) transcriptome sequencing results revealed a close association between METTL3 and tumor angiogenesis." (PMID 39295872, 2024). "Loss of m6A methyltransferase METTL3 alters NK cell homeostasis and inhibits NK cell infiltration and function in the tumor microenvironment." (PMID 39403369, 2024). "M2-tumor-associated macrophages promote METTL3 expression and increase the m6A RNA content of TNF receptor-associated factor 5 (TRAF5), affecting the tumor microenvironment, promoting necroptosis, and leading to acquired oxaliplatin tolerance." (PMID 38988324, 2024). "METTL3, the primary m6A methyltransferase, has garnered significant attention in recent years due to its involvement in various tumours and its association with tumour metastasis." (PMID 38238831, 2024). "Different molecular subtypes of GC patients overexpress different core genes for METTL3 methylation, and the tumor mutational burden (TMB) and infiltration of immune cells are also not static." (PMID 39678510, 2024).